LMO1 (LIM domain only 1)
Diseases named in the same sentence as LMO1 in open-access papers (continued):
Sharing a sentence is not in itself a finding about the gene and the disease.
glioma (continued). "Moreover, in the TGGA and GSE16011 databases, higher expression of levels of LMO1 were observed in higher grade glioma or GBM samples than those in low grade glioma and normal samples." (PMID 35280742, 2022). "In this study, we showed that LMO1was highly expressed in gliomas, especially in malignant glioblastoma, and found that the expression of LMO1 increased as the overall survival of patients decreased, which demonstrated that LMO1 plays a significant role in the malignancy of glioma." (PMID 35280742, 2022). "Furthermore, the results further indicated that the mRNA expression levels of LMO1 were significantly increase with the rise in the grade of glioma and that the expression level was highest in the group of WHO IV." (PMID 35280742, 2022). "However, the exact mechanism of LMO1 regulating NGFR transcription in mediating glioma invasion and progression still needs to be explored." (PMID 35280742, 2022). "Results of Kaplan-Meier survival analyses stratifified by the status of common genetic aberrations of glioma showed that the effect of LMO1 on patients’ prognosis was correlated with several molecular features including IDH methylation and 1p/19q non-codeletion." (PMID 35280742, 2022). "Collectively, these results indicate that LMO1 could be an independent prognostic factor for human glioma." (PMID 35280742, 2022). "Given that the increase in NGFR levels can significantly elevate the phosphorylation of p65 in LMO1 KD cells, this mean that LMO1 may be a key regulator of glioma proliferation and invasion." (PMID 35280742, 2022). "In vitro and in vivo assays were used to explore the function of LMO1 in human glioma." (PMID 35280742, 2022). "In vitro, our results validate that LMO1 could promote glioma cells proliferation, migration and invasion." (PMID 35280742, 2022). "This is the first report of LMO1 as a prognostic predictor and its function in human glioma cells." (PMID 35280742, 2022). "We found that LMO1 expression is significantly increased in more aggressive gliomas." (PMID 35280742, 2022). "The impact of LMO1 expression on patients’ survival stratified by these molecular features showed that LMO1 expression could delineate glioma patients together with same other specific genetic alterations." (PMID 35280742, 2022). "However, the clinical significance and potential mechanism of LMO1 in human gliomas remain to be determined." (PMID 35280742, 2022). "Finally, The nomogram based on the LMO1 signature for overall survival (OS) prediction in human glioma patients exhibited good performance in the individual mortality risk." (PMID 35280742, 2022). "However, it was unclear whether LMO1 could affect the migration and invasive ability of glioma cells to influence patient prognosis." (PMID 35280742, 2022). "Thus, high LMO1 expression was correlated with an increased tumor grade in glioma patients." (PMID 35280742, 2022). "The detection of several molecular markers, including IDH1 mutation, 1p/19q codeletion, MGMT promoter methylation status has been applied with clinical diagnoses of gliomas, we analyzed whether LMO1 expression was correlated with some molecular genetic characteristics by using CGGA database." (PMID 35280742, 2022). "A total of 693 tumor samples from glioma patients and 20 normal samples from CGGA databases were analyzed, The data indicated that expression level of LMO1 was higher in tumor samples than in control samples." (PMID 35280742, 2022). "The present study first investigated the LMO1–NGFR–NF-kB axis regulate cell growth and invasion in human glioma cells, whereby targeting this pathway may be a therapeutic target for glioma." (PMID 35280742, 2022). "A moderate positive correlation existed between the LMO1 expression and NGFR in glioma patients." (PMID 35280742, 2022). "High levels of LMO1 mRNA were correlated with poor prognosis in patients with isocitrate dehydrogenase (IDH)-wild-type (wt) and 1p/19q non-codeletion gliomas." (PMID 35280742, 2022).
hepatocellular carcinoma (2 papers, 2020 to 2024). A malignant tumor that arises from hepatocytes. "Genome-wide screen by CRISPRa library in vivo for drivers of hepatocellular carcinoma (HCC) progression revealed that overexpression of XAGE1B, PLK4, LMO1 and MYADML2 genes promoted HCC cell proliferation and invasion, which were suppressed by their inhibition." (PMID 39696697, 2024).
lymphoma (2 papers, 2012 to 2022). A malignant (clonal) proliferation of B- lymphocytes or T- lymphocytes which involves the lymph nodes, bone marrow and/or extranodal sites.
melanoma (2 papers, 2017 to 2024). A malignant, usually aggressive tumor composed of atypical, neoplastic melanocytes. "Ectopic WT-Bmal1 and dHLH-Bmal1 increased genes associated with mesenchymal melanoma state, such as Sox9, Fn1, Col1a1, Prrx2, Klf4, Snai2, Twist2, Lmo1 and Axl31." (PMID 38245503, 2024). "We validated μ-cisTarget by re-analyzing the TAL1 and LMO1 enhancer mutations in T-ALL, and the TERT promoter mutation in melanoma." (PMID 28854983, 2017).
Wilms tumor (2 papers, 2017 to 2024). An embryonal neoplasm characterized by the presence of epithelial, mesenchymal, and blastema components. "Regarding the LMO1 gene, rs2168101 G > T polymorphism was associated with Wilms tumor susceptibility." (PMID 38937681, 2024). "In contrast, in the recessive model (adjusted OR = 1.79, 95% CI = 1.25–2.57, P = 0.001), carriers with the LMO1 rs2168101 TT genotype seemed to have an increased risk of Wilms tumor according to an adjusted OR of 1.79." (PMID 38937681, 2024). "It is likely that rs2168101 G > T polymorphism participated in the development of Wilms tumor by regulating corresponding LMO1 gene expression level." (PMID 38937681, 2024). "Specifically, the LMO1 rs2168101 GT/TT genotypes were found to decrease the risk of developing Wilms tumor in the dominant model (adjusted OR = 0.74, 95% CI = 0.59–0.93, P = 0.009)." (PMID 38937681, 2024). "In the present hospital-based case-control study of 145 children with Wilms’ tumor and 531 cancer-free controls, we investigated the associations of four GWAS-identified LMO1 gene polymorphisms with Wilms’ tumor susceptibility." (PMID 28881592, 2017). "Here, we performed an epidemiologic study on the associations between four LMO1 gene polymorphisms and Wilms’ tumor risk in 145 affected children and 531 healthy children." (PMID 28881592, 2017). "We then genotyped the Wilms’ tumor patients and cancer-free controls for four LMO1 gene polymorphisms (rs110419 A>G, rs4758051 G>A, rs10840002 A>G and rs204938 A>G)." (PMID 28881592, 2017). "We further evaluated the relationship between the LMO1 risk genotypes and Wilms’ tumor susceptibility in subjects stratified by age, gender, and clinical stage." (PMID 28881592, 2017). "Our study was the first to investigate the associations of LMO1 gene polymorphisms with Wilms’ tumor risk in a Chinese population." (PMID 28881592, 2017). "When biologically functional SNP in LMO1 gene was mutated, the expression of corresponding genes might be affected and was related to the occurrence of Wilms tumor." (PMID 38937681, 2024). "In contrast, subjects carrying the LMO1 rs2168101 TT genotype might have an increased risk of Wilms tumor in the recessive model (adjusted OR = 1.79, 95% CI = 1.25–2.57, P = 0.001)." (PMID 38937681, 2024). "In addition to a replication study of the LMO1 gene in a larger population, we also need further investigation to validate the associations between other underlying SNPs in the LMO1 gene and Wilms tumor susceptibility." (PMID 38937681, 2024). "Moreover, another SNP in the LMO1 gene, rs11603024 C > T, was detected to increase Wilms tumor risk in a recessive model (adjusted OR = 4.29, 95% CI = 2.08–8.84, P < 0.0001)." (PMID 38937681, 2024). "Moreover, another SNP locus in the LMO1 gene, rs11603024 C > T, was detected to confer enhanced susceptibility to Wilms tumor in recessive model." (PMID 38937681, 2024). "Furthermore, other LMO1 gene variants and gene-environment interactions should be investigated to provide essential insights into the etiology of Wilms’ tumor." (PMID 28881592, 2017). "Thus, we examined the associations between these LMO1 polymorphisms and Wilms’ tumor risk in Southern Chinese children." (PMID 28881592, 2017). "In conclusion, we determined that the rs110419 AG polymorphism in LMO1 may reduce the susceptibility to Wilms’ tumor in a Southern Chinese population." (PMID 28881592, 2017). "We examined the associations between LMO1 gene polymorphisms and susceptibility to Wilms’ tumor." (PMID 28881592, 2017). "Additionally, given the structural similarity of the LMO gene family, we reasonably speculated that LMO2 and LMO4 gene polymorphisms might be correlated to Wilms tumor susceptibility as LMO1 gene did." (PMID 38937681, 2024). "Thus, LMO1 gene polymorphisms may contribute to Wilms’ tumor risk, but this conclusion should be validated in other populations and larger studies." (PMID 28881592, 2017).
Wilms tumor (continued). "Previous GWAS and candidate gene approaches have discovered some susceptible genes correlated with the predisposition to Wilms tumor, such as METTL3, ALKBH5, BRAD1, PHOX2B, and LMO1." (PMID 38937681, 2024). "We found LMO1 rs2168101 G > T and rs11603024 C > T as well as LMO2 rs7933499 G > A were significantly associated with Wilms tumor risk." (PMID 38937681, 2024). "Considering the critical effect of LMO1 gene polymorphisms on tumor risk, our team has spared no effort to investigate the relationship between LMO1 gene polymorphisms and Wilms tumor susceptibility." (PMID 38937681, 2024). "In brief, the current epidemiological genetic association study identified that several functional SNPs in the LMO family genes, namely, rs2168101 G > T and rs11603024 C > T in the LMO1 gene and rs7933499 G > A in the LMO2 gene, are significantly associated with susceptibility to Wilms tumor." (PMID 38937681, 2024). "Despite the growing body of research demonstrating the associations of LMO1 gene variants with cancer susceptibility, until now, no study had investigated the relationship between LMO1 polymorphisms and Wilms’ tumor risk." (PMID 28881592, 2017). "A GWAS regarding LMO1 gene SNPs and Wilms’ tumor remains to be performed." (PMID 28881592, 2017). "The results indicated that LMO1 and LMO2 genetic variants were associated with Wilms tumor susceptibility, which may help identify additional genetic susceptibility loci as novel biomarkers for the diagnosis and treatment of Wilms tumor." (PMID 38937681, 2024).
cervical cancer (1 paper, 2022). A primary or metastatic malignant neoplasm involving the cervix. "RIP assay using DHX9 antibody showed that intron 1 and intron 3 of LMO1 are significantly enriched, indicating that up-regulated DHX9 results in a decrease in circLMO1 in cervical cancer." (PMID 35321435, 2022).
coronary artery disease (1 paper, 2025). "LMO1 has previously been associated with other metabolic traits such as systolic and diastolic blood pressure 28, fasting blood glucose 29, body mass index 30 and birth weight 31 but not coronary artery disease." (PMID 39974115, 2025).
hyperlipidemia (1 paper, 2025). "However, we do identify putative genetic markers potentially important for disease progression such as the variant in LMO1 which protects from progressing from a hyperlipidemia to CABG surgery." (PMID 39974115, 2025). "However, we identify additional variants such as a common variant downstream of LMO1 (rs11041816) that protects against progression from a hyperlipidemia diagnosis to undergoing coronary artery bypass graft (CABG)." (PMID 39974115, 2025).
meningioma (1 paper, 2026). A generally slow growing tumor attached to the dura mater. "Meningiomas in infants and toddlers are exceedingly uncommon, and the presence of a YAP1::LMO1-rearranged atypical meningioma in a 16-month-old patient in our cohort further illustrates the distinctive clinical and molecular features seen in this age group." (PMID 41526775, 2026).
metastatic disease (1 paper, 2023). "Later, this model was used to lay the foundation for the current study, providing definitive evidence that LIM-domain-only 1 (LMO1) synergizes with MYCN to result in a more penetrant and aggressively metastatic disease." (PMID 37183823, 2023).
retinoblastoma (1 paper, 2013). A malignant tumor that originates in the nuclear layer of the retina. "Within the recurrent focal gains or losses in the RbTKO retinoblastoma model, we found 12 in cancer genes, including Lmo1 in 5/6 samples; Ndrg1, Brd4, Fbxo11, and Rbm15 in 4/6 samples; Mdm4, Msi2, and Ezh2 in 3/6 samples." (PMID 23765217, 2013). "However, LMO1 is not altered in human retinoblastoma at the genomic, epigenomic or transcriptional level." (PMID 23765217, 2013).
tumor (27 papers, 2014 to 2025). "The NB cell line KCNR contains the G risk allele associated with tumor LMO1 SE and became a Lost SE cluster candidate." (PMID 38653778, 2024). "Previous genome-wide association study (GWAS) identified that LIM domain only 1 (LMO1) gene polymorphisms affected the susceptibility to develop certain tumor types." (PMID 38937681, 2024). "Currently, among the LMO family genes, genetic associations between LMO1 gene polymorphisms and tumor susceptibility have been most intensively studied." (PMID 38937681, 2024). "They now demonstrate experimentally, using genome-edited zebrafish, that a polymorphism in the human rs2168101 locus of the LMO1 gene determines which CRC is active in a tumor." (PMID 37183823, 2023). "Analysis of the available RNA-seq data showed that the T-ALL tumour with the LMO1 enhancer mutation had the sixth highest expression level of LMO1 relative to the 264 T-ALLs analysed in the NCI TARGET, consistent with the cancer cell line data." (PMID 28260788, 2017). "Aberrant LMO1 was associated with more advanced disease, and the ancestral rs2168101 G allele was associated with tumor formation." (PMID 27009839, 2016). "High LMO1 expression was associated with a high tumor grade and a poor prognosis in patients." (PMID 35280742, 2022). "This is supported by the fact that the lmo1–/– tumor cells fail to show signs of Notch signaling, which is very important to induce the mesenchymal CRC." (PMID 37183825, 2023). "We have demonstrated that LMO1 overexpression synergizes with MYCN to accelerate tumor onset, penetrance, and metastasis in a dβh:MYCN- driven zebrafish model." (PMID 37183825, 2023). "The heterozygous lmo1+/– fish showed an intermediate tumor penetrance, with 41% of fish developing tumors at 17 weeks." (PMID 37183825, 2023). "MRI scan and Haematoxylin and eosin (HE) staining of intracranial tumour-bearing mice at 3 weeks after implantation suggested that compared with the control conditions, LMO1 knockdown impaired tumor growth." (PMID 35280742, 2022). "Consistently, the nude mice study further confirmed that knockdown of LMO1 blocked tumor growth via NGFR-NF-kB axis." (PMID 35280742, 2022). "As it has been shown earlier in the zebrafish NB model, overexpression of LMO1 upregulates the expression of genes affecting tumor cell-extracellular matrix interaction and promotes NB cell invasion and migration." (PMID 33800887, 2021). "In investigating the clinical relevance of LMO1 as an oncogene, we found that a high tumor level of the LMO1 mRNA was an independent predictor of poor patient survival." (PMID 30038707, 2018). "The modest enhancement of LMO1 in T-ALL induction by SCLm13 remains compatible with a tumor suppressor function for E proteins." (PMID 25522233, 2014). "LMO1 can also act as an activated tumor promoter that activates AKT signaling in NSCLC." (PMID 36901953, 2023). "In addition, a reduction in the proliferation and invasion signature genes (ki67,vimentin) were observed in tumour with downregulated LMO1." (PMID 35280742, 2022). "Gene silencing of LMO1 significantly inhibited tumor growth, invasion and migration in vitro." (PMID 35280742, 2022). "Importantly, LMO1 knockdown reduced the progression of xenograft tumor growth and prolonged overall survival in nude mice bearing intracranial tumors." (PMID 35280742, 2022). "In contrast, LMO1 over-expression promoted tumor growth, invasion and migration." (PMID 35280742, 2022). "In transgenic fish with overexpression of MYCN and LMO1 oncogenes, fluorescent-positive tumor masses were observed using fluorescent microscopy in the distant regions from the primary tumor site, the interrenal gland region (IRG), as early as five weeks of age." (PMID 33800887, 2021). "The authors previously showed that overexpression of LIM-domain-only 1 (LMO1), a transcriptional coregulator, synergizes with MYCN to accelerate tumor formation and metastasis in an NBL-zebrafish model." (PMID 37183823, 2023).
tumor (continued). "Together, our results indicate a tumor suppressor function for Heb which acts in a gene-dosage dependent manner in T-ALL induced by SCL and LMO1." (PMID 35401501, 2022). "LMO1, RP11-834C11.12, MAN1A2P1, HTRA3 and ESR1 were the top five differentially hypermethylated genes in primary tumours compared to NAT." (PMID 32971738, 2020). "Conversely, TQ treatment resulted in the downregulation of several genes overexpressed in GBM cells, including potential oncogenes like AEBP1, MIAT, GHR, LMO1, ELF3, and genes involved in tumor proliferation and migration such as EPHA4, COL3A1, PCDH10, ROBO1, ADAMTS5, PCDH18, ST8SIA1." (PMID 39874307, 2025). "These additional targets may account for the more prominent role of HEB as a tumor suppressor in response to the oncogenic stress induced by SCL and LMO1, exactly at the β-selection checkpoint controlled by HEB." (PMID 35401501, 2022). "In addition, the hematogenous metastases of tumor cells to the similar common sites of metastases seen in patients were also observed in the transgenic fish lines with overexpression of MYCN and LMO1 or LIN28B." (PMID 33800887, 2021). "Importantly, expression of the other 6 highly related zebrafish lmo family members — lmo2, lmo3, lmo4a, lmo4b, lmo5, lmo6, lmo7a, and lmo7b — was much lower than lmo1 in the GATA/GATA fish and showed no appreciable differences between the 3 tumor genotypes." (PMID 37183825, 2023).